PTGR1 (prostaglandin reductase 1)
Description:
NAD(P)H-dependent oxidoreductase involved in metabolic inactivation of pro- and anti-inflammatory eicosanoids: prostaglandins (PG), leukotrienes (LT) and lipoxins (LX). Catalyzes with high efficiency the reduction of the 13,14 double bond of 15-oxoPGs, including 15-oxo-PGE1, 15-oxo-PGE2, 15-oxo-PGF1-alpha and 15-oxo-PGF2-alpha. Catalyzes with lower efficiency the oxidation of the hydroxyl group at C12 of LTB4 and its derivatives, converting them into biologically less active 12-oxo-LTB4 metabolites (By similarity). Reduces 15-oxo-LXA4 to 13,14 dihydro-15-oxo-LXA4, enhancing neutrophil recruitment at the inflammatory site (By similarity). May play a role in metabolic detoxification of alkenals and ketones. Reduces alpha,beta-unsaturated alkenals and ketones, particularly those with medium-chain length, showing highest affinity toward (2E)-decenal and (3E)-3-nonen-2-one. May inactivate 4-hydroxy-2-nonenal, a cytotoxic lipid constituent of oxidized low-density lipoprotein particles (By similarity).
Synonyms: DIG-1; LTB4DH; ZADH3; PGR1
Tractability: Small molecule: a structure with a bound ligand is known; it has a high-quality binding pocket. PROTAC: ubiquitination databases record sites on it; its protein half-life has been measured.
Target class: Enzyme; Oxidoreductase
Gene: Protein-coding gene on chromosome 9 (111,549,722 to 111,599,893, reverse strand). Ensembl gene ENSG00000106853.
Subcellular location: Cytoplasm
Pathways (Reactome):
Metabolism: Biosynthesis of Lipoxins (LX); Synthesis of Leukotrienes (LT) and Eoxins (EX)
Gene Ontology:
Molecular function: 15-oxoprostaglandin 13-reductase [NAD(P)+] activity; 2-alkenal reductase (NADPH) activity; protein binding; 13-lipoxin reductase activity; leukotriene B4 12-hydroxy dehydrogenase activity; 2-alkenal reductase [NAD(P)H] activity; oxidoreductase activity; oxidoreductase activity, acting on the CH-CH group of donors, NAD or NADP as acceptor
Biological process: prostaglandin metabolic process; leukotriene B4 metabolic process; leukotriene metabolic process; lipoxin A4 metabolic process
Cellular component: extracellular exosome; cytoplasm
Genetic constraint (gnomAD): Loss-of-function variants: 17 observed, 31.8 expected, observed/expected ratio (o/e) 0.53, 90% interval 0.37 to 0.8. The upper end of that interval is the gene's LOEUF score, 0.8, which puts it in group 3 of 6, group 1 being the genes least tolerant of losing a copy. Missense variants: 335 observed, 383.97 expected, observed/expected ratio (o/e) 0.87, 90% interval 0.8 to 0.95. Synonymous variants: 126 observed, 136.73 expected, observed/expected ratio (o/e) 0.92, 90% interval 0.8 to 1.07.
Homologues: Orthologues: chimpanzee PTGR1 (99% identical), dog PTGR1 (86% identical), pig PTGR1 (84% identical), macaque PTGR1 (82% identical), mouse Ptgr1 (81% identical), rat Ptgr1 (74% identical), rabbit PTGR1 (68% identical), tropical clawed frog ptgr1.4 (62% identical), tropical clawed frog ptgr1.2 (61% identical), zebrafish ptgr1.1 (60% identical), guinea pig PTGR1 (57% identical), zebrafish ptgr1.2 (54% identical), and 3 more. Paralogues in human: PTGR2 (39% identical), PTGR3 (21% identical), CRYZ (21% identical), RTN4IP1 (21% identical), VAT1 (20% identical), ADH1C (20% identical), MECR (20% identical), ADH1B (20% identical), VAT1L (19% identical), TP53I3 (19% identical), ADH1A (19% identical), ADH5 (19% identical), and 5 more.